SIRT1 (sirtuin 1)
Diseases named in the same sentence as SIRT1 in open-access papers (continued):
Sharing a sentence is not in itself a finding about the gene and the disease.
non-small cell lung carcinoma (40 papers, 2013 to 2025). A group of at least three distinct histological types of lung cancer, including non-small cell squamous cell carcinoma, adenocarcinoma, and large cell carcinoma. "This study was to explore the association between the SIRT1 expression and the clinical characteristics, the responsiveness to chemotherapy and prognosis in Non-small cell lung cancer (NSCLC)." (PMID 24223900, 2013). "Additionally, SIRT1 expression was significantly associated with poorer differentiation status in advanced non-small cell lung cancer, indicating that SIRT1 expression was parallel with the tumor severity." (PMID 26999517, 2016). "Treatment with the resveratrol (10–50 μM) activated chromatin-associated SIRT1 protein on the cIAP-2 promoter region, which resulted in a loss of NF-κB-regulated gene expression and consequently augmented the tumor necrosis factor α (TNFα)-induced apoptosis in human non-small-cell lung cancer cells." (PMID 28600541, 2017). "Recently, a study reported that hsa-miR-217 expression plays a tumour suppressor role in non-small cell lung cancer cells by targeting SIRT1." (PMID 39057123, 2024). "Alike, it was revealed that miR-30e-5p depletes the occurrence of non-small cell lung cancer by downregulating ubiquitin-specific peptidase 22 and affecting the sirtuin 1/Janus kinase/signal transducer and activator of transcription 3 signaling pathway." (PMID 35300562, 2022). "SIRT1 silencing dramatically suppresses the proliferation of non-small cell lung cancer (NSCLC) cells by decreasing p27/Kip1 protein stability." (PMID 34407842, 2021). "In this current article, we focused on the relationship between cisplatin resistance and SIRT1 protein expression in cisplatin resistance non-small cell lung cancer cells (A549)." (PMID 32489467, 2020). "In non-small cell lung cancer (NSCLC), expression of SIRT1 and SIRT2 is associated with poor prognosis." (PMID 32117717, 2020). "A recent study showed that SIRT1 regulates the hypoxia-induced resistance of non-small cell lung cancer to cisplatin and doxorubicin." (PMID 32489686, 2020). "Hsa-miR-217 and its target sirtuin 1 acted as metastasis suppressor and promoter gene in non-small cell lung cancer, respectively." (PMID 32267139, 2020). "Sirtuin 1 and hsa-miR-217 have been identified to mediate the development of non-small cell lung cancer." (PMID 32267139, 2020). "It has been shown that BAL inhibits the proliferation and migration of human non-small cell lung carcinoma cells through activation of the SIRT1/AMPK signaling pathway." (PMID 31722718, 2019). "In contrast, SIRT1 is downregulated in non-small cell lung cancer cells exposed to hypoxia, where it modulates the chemotherapeutic resistance to cisplatin and doxorubicin." (PMID 31068761, 2019). "Silencing SIRT1 suppressed non-small-cell lung cancer cell proliferation and dramatically suppressed tumor formation." (PMID 29752439, 2018). "Particularly, the LAT1-NAD+-SIRT1 signaling is activated in tumor tissues of patients with non-small cell lung cancer." (PMID 27566573, 2016). "The present study focused on how SIRT1 expression influence the senstivity of non-small cell lung cancer cells and dissected the potential mechanism involved with Noxa." (PMID 26903157, 2016). "Luteolin is a falconoid compound, which exhibits anticancer properties, however, its contribution to Sirt1-mediated apoptosis in human non-small cell lung cancer remains to be elucidated." (PMID 26096576, 2015). "On the other hand, other studies indicate that SIRT1 may contribute to the progression of non-small cell lung cancer via the Phosphoinositide 3-Kinase/Protein Kinase B (PI3K/AKT) signaling pathway." (PMID 41154674, 2025). "The abnormal expression of SIRT1 was involved in the development of non-small-cell lung cancer." (PMID 32489686, 2020).
non-small cell lung carcinoma (continued). "While searching for the mechanisms of these reactions, it has been proven that SirT1 regulates apoptosis and radio-sensitivity of cells through the Sirt1/NF-κB/Smac pathway that may be a potential target in the treatment of non-small-cell lung carcinoma." (PMID 31027322, 2019). "Similarly, radiosensitivity and apoptosis were induced by miR-22-mediated inhibition of SIRT1 in breast cancer cells, by miR-34a-mediated inhibition of LyGDI in non-small cell lung cancer (NSCLC) cells and by miR-124-mediated inhibition of CDK4 in ESCC and glioma cells." (PMID 32585857, 2020). "Tenovin-6, an SIRT1 inhibitor, in combination with metformin, an activator of AMP-activated protein kinase (AMPK), inhibits growth in non-small cell lung cancer (NSCLC) cells." (PMID 34769241, 2021). "Other studies have also shown that the combination of SIRT1 and SIRT2 is a better predictive model of recurrence-free survival (RFS) in non-small cell lung cancer (NSCLC) to stratify patients." (PMID 31932479, 2020). "Interestingly, the protein expression level of ISG15 showed a subtle yet significant positive correlation with the protein expression level of SIRT1 in the complete set of cancer types (R = 0.15, P = 0.0042) as well as in non-small cell lung carcinoma (NSCLC) (R = 0.26, P = 0.0441)." (PMID 38443596, 2024). "Similarly, SIRT1 contributes to p65 deacetylation in glucose-induced podocyte EMT, whereas OPN can inhibit SIRT1 expression and promote p65 acetylation in non-small cell lung cancer cells." (PMID 35484625, 2022).
liver diseases (37 papers, 2016 to 2025). "As the understanding of the structural and functional dynamics of SIRT1 continues to evolve, its relevance in disease prevention and treatment is becoming increasingly apparent, particularly in the context of liver diseases associated with aging and metabolic dysfunction." (PMID 40052151, 2025). "While other sirtuins, such as SIRT2, SIRT3, and SIRT6, contribute to processes like chromatin remodeling, oxidative stress regulation, and DNA repair, this review focuses on SIRT1 due to its critical involvement in cellular mechanisms, particularly in liver diseases associated with aging." (PMID 40052151, 2025). "Further, SIRT1 seems to cause divers outcomes in different types of liver diseases." (PMID 38563003, 2024). "This section provides a systematic overview of the functional roles of SIRT1 in various common liver diseases." (PMID 41281762, 2025). "This review aims to provide a comprehensive overview of the role of SIRT1-mediated aging in liver diseases and its impact on liver disease progression." (PMID 40052151, 2025). "As research progresses, the role of SIRT1 in regulating physiological processes in liver diseases has become increasingly evident." (PMID 41281762, 2025). "Although the protective role of SIRT1 in liver diseases is evident, its precise mechanisms of action remain to be fully understood." (PMID 40052151, 2025). "In liver diseases, SIRT1-dependent epigenetic regulation plays a central role in modulating cellular metabolism, senescence, and disease progression through mechanisms such as DNA methylation, histone modifications, and interactions with microRNAs (miRNAs)." (PMID 40052151, 2025). "In cholestasis-induced liver disease, SIRT1 activation alleviates mitochondrial dysfunction, reduces apoptosis, and suppresses oxidative stress, all of which contribute to fibrosis and liver aging." (PMID 40052151, 2025). "Continued research into SIRT1’s regulatory functions will provide essential insights into preventing and treating liver diseases." (PMID 40052151, 2025). "As research advances, SIRT1 has garnered widespread attention in the study of various liver diseases." (PMID 41281762, 2025). "One of the most promising approaches for targeting SIRT1 in liver disease involves using SIRT1 activators, which aim to boost SIRT1’s protective effects." (PMID 40052151, 2025). "SIRT1 also promotes mitophagy, clears damaged mitochondria, prevents aging-related liver diseases, and improves cellular energy metabolism." (PMID 40052151, 2025). "Even though SIRT1 has undergone comprehensive research in aging and metabolic modulation, its specific functions and regulatory mechanisms in various liver disease settings remain incompletely understood." (PMID 41281762, 2025). "SIRT1 is a pivotal regulator of ferroptosis in liver disease, playing a crucial role in maintaining hepatic health." (PMID 40109363, 2025). "With the continual advances in our understanding of pathophysiology, the pivotal mechanisms by which SIRT1 modulates liver disease progression have become increasingly evident." (PMID 41281762, 2025). "In recent studies, accumulating data have demonstrated that SIRT1 is crucial for preserving normal liver function and influencing liver disease progression." (PMID 41281762, 2025). "Recent research has focused on exploring the function and molecular mechanisms of SIRT1 in liver diseases, aiming to comprehensively understand its roles in liver pathophysiology." (PMID 41281762, 2025). "In recent years, accumulating evidence has highlighted the critical involvement of SIRT1 dysregulation in the pathogenesis of various liver diseases." (PMID 41281762, 2025). "Ultimately, the convergence of mechanistic insights, advanced delivery technologies, and clinical rigor will be essential for the development of next-generation SIRT1-targeted therapies in liver diseases." (PMID 41281762, 2025).
liver diseases (continued). "As a member of the Sirtuin family, SIRT1 has emerged as a key therapeutic target for aging-related liver diseases." (PMID 40052151, 2025). "Overall, the CRISPR system represents a powerful approach for generating SIRT1 gene‐edited models, as well as a potential therapeutic strategy for targeting SIRT1 in the treatment of liver diseases." (PMID 41281762, 2025). "Of note, during the progression from steatotic liver disease to fibrosis, SIRT1 downregulation in parenchymal hepatocytes and Kupffer cells leads to lipid metabolic disturbances that facilitate HSCs activation." (PMID 41281762, 2025). "We also discuss emerging therapeutic approaches, including SIRT1 activators, gene therapy, and nutritional interventions, which are evaluated for their potential to restore SIRT1 function and mitigate liver disease progression." (PMID 40052151, 2025). "As SIRT1 activity declines with age, mitochondrial dysfunction worsens, increasing ROS production and energy conservation and accelerating liver disease progression." (PMID 40052151, 2025). "This review will help researchers in molecular biology or hepatic disease fully understand the role of SIRT1 in various liver diseases and the methods of interfering with liver diseases through SIRT1 in recent years." (PMID 38563003, 2024). "These discrepancies underscore the need for further research to unravel the intricate mechanisms of SIRT1’s action in liver diseases." (PMID 38563003, 2024). "Such insights will be crucial in harnessing SIRT1’s full potential as a novel and effective therapeutic target for liver diseases." (PMID 38563003, 2024). "Despite the research on the action of SIRT1 on ferroptosis in liver disease is limited, it has been indicated that ulinastatin can protect against acetaminophen-induced liver damage by minimizing ferroptosis via activating the SIRT1/NRF2/HO-1 pathway." (PMID 37305039, 2023). "Clinically, SIRT1 is significantly downregulated in hepatic disorders compared with that in normal patients." (PMID 37324954, 2023). "Previous research showed that Sirt1 mediated cancer, liver disease and mitophagy via regulating mTORC1." (PMID 37670386, 2023). "Our findings underscore a novel molecular insights into MSCs-mediated immunomodulation by activating Notch2/COX2/AMPK/SIRT1 pathway and thus provide a new strategy for the treatment of liver inflammatory diseases." (PMID 35842731, 2022). "A parallel Sirt1 dysregulation has also been reported in a wide range of rodent models of liver diseases, including α-Naphthylisothiocyanate, thioacetamide, and carbon tetrachloride." (PMID 35624826, 2022). "SIRT1 is correlated with mitochondrial function, energy metabolism, autophagy, apoptosis, and oxidative stress processes and plays a significant role in liver diseases." (PMID 36139752, 2022). "More specific and novel molecular targets of alpinetin in hepatic disorders therapy are required to be illustrated in further experiments, such as glucagon-like peptide-1 (GLP-1), Sirtuin 1 (SIRT1), Yes-associated protein (YAP), etc." (PMID 35185569, 2022). "SIRT1, a histone deacetylase in sirtuin family proteins, is involved in nucleophagy and is beneficial for improving liver diseases." (PMID 36497176, 2022). "Recent studies demonstrated that AMPK/SIRT1 activation plays an important protective role in ethanol-mediated liver diseases." (PMID 33162823, 2020). "In this review, we explore diverse upstream regulators and some natural/synthetic activators of SIRT1 as possible therapeutic treatment for liver diseases." (PMID 32485811, 2020). "Collectively, our study suggests that increasing SIRT1 expression in either parent can attenuate the metabolic and liver disorders induced in offspring by maternal high-fat diet feeding." (PMID 33027895, 2020). "We and others have described SIRT1 as being highly expressed in human liver tumors, pointing to the potential contribution of SIRT1 to liver disease." (PMID 30229970, 2019).
liver diseases (continued). "Consistent with the prominent role of cathepsin/SIRT1, cysteine cathepsin inhibition limits NF-κB-dependent hepatic inflammation through the regulation of SIRT1 in all in vivo settings, providing a novel anti-inflammatory therapeutic target in liver disease." (PMID 27831566, 2016). "In future research, exploring the precise upregulation of SIRT1 through CRISPRa to ameliorate certain liver diseases, such as MASLD, may represent a feasible and promising strategy." (PMID 41281762, 2025). "Similarly, the Qing'E formula, a traditional prescription used since the Song dynasty, has demonstrated potential in modulating SIRT1 activity and reducing inflammation and oxidative stress in liver diseases." (PMID 40052151, 2025). "Summary of SIRT1 modulators and their aging-related mechanisms in liver diseases." (PMID 40052151, 2025). "Furthermore, the pleiotropic roles of SIRT1, particularly its immunomodulatory properties, can lead to divergent outcomes depending on the type and stage of liver disease." (PMID 41281762, 2025). "Collectively, SIRT1 may exert divergent roles in PI3K/Akt signaling under different pathological conditions of liver disease." (PMID 41281762, 2025). "Therapeutic strategies targeting SIRT1 could therefore provide significant benefits in slowing liver disease progression by reducing cellular senescence and enhancing tissue repair." (PMID 40052151, 2025). "The findings above indicate that SIRT1-targeted therapies could serve as innovative approaches for treating various liver diseases by modulating ferroptosis pathways." (PMID 40109363, 2025). "Notably, SIRT1 levels naturally decline with age, contributing to liver disease progression and increased vulnerability to injury." (PMID 40052151, 2025). "In conclusion, the NF-κB signaling pathway plays a crucial regulatory role in the progression of liver diseases, and a deeper understanding of SIRT1's involvement in the NF-κB signaling pathway offers great potential for developing novel strategies and therapies for liver diseases." (PMID 41281762, 2025). "Similarly, given the extensive research on liver-targeted nano-based drug delivery systems, encapsulating SIRT1 modulators into specially designed liver-targeted functionalized nanocarriers represents a promising strategy for the treatment of liver diseases." (PMID 41281762, 2025). "Despite the established role of SIRT1 in liver disease, many aspects remain unclear, particularly its adaptive function." (PMID 38563003, 2024). "Specifically, Sirtuin1 (SIRT1), a member of the sirtuin protein family, has been extensively studied in the context of liver injury in recent years and are confirmed the significant role in liver disease." (PMID 38563003, 2024). "The effect of several dual SIRT1/2 inhibitors have also shown positive outcomes in liver diseases." (PMID 38993557, 2024). "Recent study demonstrated that SIRT1 activation could protect against alcohol-induced liver diseases." (PMID 30200508, 2018). "Aberrant SIRT1 over-expression could be targeted inmetabolic liver disease involving dysregulated bile acidmetabolism." (PMID 27508069, 2016). "Additionally, compounds such as PL 1-3 and Empagliflozin have garnered attention for their ability to upregulate SIRT1, enhance mitochondrial function, and reduce oxidative stress and senescence markers, thereby mitigating the progression of liver diseases such as MASLD." (PMID 40052151, 2025). "Therefore, SIRT1 or Nrf2 activation may be a significant target for reducing inflammation in liver diseases." (PMID 37627483, 2023). "We hypothesize that A. indica oil prevented the OTA-induced liver disorders by regulating the protein carbonyl content (PC), protein peroxidation, and protein expression of the SIRT1-mediated PGC-1α pathway, inhibiting the production of cytokines and decreasing oxidative disorders." (PMID 36139752, 2022).
liver diseases (continued). "Thus, our findings suggest an effective strategy to prevent and/or treat liver inflammatory diseases by modulating the AMPK/SIRT1 pathway and targeting the XBP1/NLRP3 activity in macrophages using genetically modified MSC approaches or pharmacological interventions." (PMID 35842731, 2022). "The sirtuin family, consisting of seven members (SIRT1–7), plays a crucial role in inhibiting MASLD and other liver diseases." (PMID 40507912, 2025). "Overall, this effect of SIRT1 and SIRT2 in liver diseases including NAFLD, has been observed to be similar." (PMID 38993557, 2024). "Sirtuin 1 (SIRT1), a kind of nicotinamide adenine dinucleotide (NAD+)-dependent histone deacetylase, confers protection against liver aging and liver diseases." (PMID 36497176, 2022). "Overall, SIRT1 facilitates the activation of the AMPK signaling pathway, which in turn modulates liver energy metabolism, suppresses inflammatory responses, and ultimately delays the progression of liver diseases." (PMID 41281762, 2025). "Intriguingly, SIRT1 exhibits different characteristics and functions depending on the type of liver disease, revealing a level of adaptability that is not yet fully understood." (PMID 38563003, 2024). "Other studies regarding upstream regulators of SIRT1, such as IRF9/PPAR-α, NAMPT/NMNAT, HuR, AMPK, PARP1, CK2 and cathepsins have pointed to these proteins as possible therapeutic targets for the treatment of various inflammatory pathologies, including liver diseases." (PMID 32485811, 2020). "Herein, we focused the potent effect of SIRT1 on ameliorating drug-induced liver injury (DILI), which may be a novel target for DILI treatment and other liver diseases, meanwhile shedding light on potent SIRT1 activators for further exploration of their roles in SIRT1 expression." (PMID 31354914, 2019).